IL1B (interleukin 1 beta)
Diseases named in the same sentence as IL1B in open-access papers (continued):
Sharing a sentence is not in itself a finding about the gene and the disease.
COVID-19 (continued). "The COVID-19 group had significantly higher levels of IFN-γ (P<0.01), IL-2 (P<0.01), IP-10 (P<0.01), IL-1β (P = 0.001), IL-6 (P = 0.002), IL-8 (P = 0.003), and TNF (P = 0.014) when compared to the unexposed healthy group." (PMID 37018291, 2023). "In the present study, we reported the clinical manifestations and inflammatory markers including cytokines (IL-6, IL-1β, and TNF-α) in 35 Turkish children with PCR-positive COVID-19." (PMID 37034144, 2023). "Various cytokines (IFN-γ, IL-1β, IL-6, IL-2, and TNF-α) had altered levels in COVID-19, and the cytokine storms correlate with the severity and progression of COVID-19." (PMID 37565145, 2023). "Our findings are in agreement with previously reported data showing increased levels of inflammatory cytokines, such as IL-1β, TNF and IFNγ, and oxidative stress together with impaired spermatogenesis in men recovering from COVID-19." (PMID 37497433, 2023). "CD14highCD16- monocytes derived from severe COVID-19 patients showed increased NLRP3 inflammasome activation potential, as shown by the formation of ASC speck/caspase-1 complexes and increased IL-1β secretion." (PMID 37251383, 2023). "Multiple studies have documented high levels of inflammatory markers and cytokines, including Interferon-gamma, Interleukin-1 beta (IL-1β), monocyte chemoattractant protein (MCP-1), IP-10, and TNF alpha, in patients of COVID-19." (PMID 37009373, 2023). "The secretion of cytokines and chemokines, including IL6, CXCL8, IL1B, IL10 and CCL2, is significantly increased in COVID-19 AKI." (PMID 37274117, 2023). "First, we measured plasma levels of 8 cytokines (IFN-α, IL-1α, IL-1β, IL-10, IL-6, IL-8, S100A8/A9 (calprotectin), and TNF-α), which were shown to be upregulated in the blood of severe COVID-19 patients." (PMID 38082066, 2023). "Our results showed that COVID-19 patients had significantly higher levels of IFN-γ, TNF, IL-1β, IL-2, IL-6, IL-8, and IP-10 than the unexposed group." (PMID 37018291, 2023). "Autopsy samples from severe COVID-19 patients display increased NLRP3-I activation in lung tissues and peripheral blood mononuclear cells, and monocytes isolated from severe COVID-19 patients have increased levels of activated NLRP3-I and IL-1β." (PMID 36891303, 2023). "Patients with severe COVID-19, as evidenced in our study, release a large amount of pro-inflammatory cytokines (IFN-α, IFN-γ, IL-1β, IL-6, IL-12, IL-18, IL-33, TNF- α, and TGF- β)." (PMID 37408032, 2023). "Early into the pandemic, those diagnosed with COVID-19 were found to display significantly elevated proinflammatory responses, including increased levels of IL-6, TNF, IL-2, IL-1β, IP-10, IFNγ, MCP1 and MIP1α." (PMID 37091818, 2023). "The differentiation of CD4+ T cells, activated by the interaction of IL-23 with TYK2/Jak2, occurs with the participation of IL-6, IL-1β and TGF-β, which is extremely important in the context of the cytokine storm in COVID-19." (PMID 37896870, 2023). "To determine the pro-inflammatory effects of S1 spike protein on BEAS-2B and A549 cells, we measured the levels of IL-1β, TNF-α, IL-6, and IL-8, crucial inflammatory cytokines in COVID-19." (PMID 37834316, 2023). "Ratios of serum levels of IL-10 and Gal-3 with IL-1β, TNF-α and IL-12 in all stages of COVID-19 were made." (PMID 36702907, 2023). "SARS-CoV-2 infection triggers extensive production of pro-inflammatory molecules such as CRP, TNF-α, IL-1β, IL-6, MIP-1α, IP-10 and IL-10 by activated inflammatory monocytes and neutrophils recruited into the lungs of COVID-19 patients." (PMID 37854602, 2023). "Levels of the inflammasome cytokine IL1B, the neutrophil chemotaxis factor CXCL8, and alarmins S100A8 and S100A9 were comparably elevated in KD and severe COVID-19 compared to FC and HC, respectively." (PMID 36159873, 2022). "IL-1β, IL-6, IL-8, TNFα and CRP in the hospitalised patients with COVID-19 (n = 76) was higher (all p<0.0001) compared to the healthy volunteers." (PMID 35500008, 2022).
COVID-19 (continued). "Initial studies in Wuhan, China showed elevated IL-1β, IL-7, IL-8, IL-9, IL-10, FGF, G-CSF, GM-CSF, IFN-γ, IP-10, MCP-1α and 1β, MIP-1, PDGF, TNF-α, and VEGF concentrations in COVID-19 compared to uninfected individuals." (PMID 35401519, 2022). "Our results demonstrate that melatonin consumption for 14 days significantly decreases plasma levels of IL-4, IL-2, IL-1β, IFN-γ, and IL-6 in COVID-19 patients." (PMID 36254292, 2022). "Increased circulating levels of the pro-inflammatory cytokines IL-1β, IL-6, IL-8, and TNF-α are hallmarks in the immunopathology of chronic inflammatory diseases, including COVID-19." (PMID 35563697, 2022). "In the present study, serum IL-1β (Th1 cytokine) was positively correlated with serum urea, CK-MB, and LDH in both moderate and severe COVID-19 patients." (PMID 35891209, 2022). "The chest CT image of COVID-19 patients showed ground-glass opacity, and compared with healthy adults, the plasma concentrations of IL-1β, IL-7, IL-8, IL-9, IL-10, IFN-γ, TNF-α, and VEGF of COVID-19 patients were all upregulated." (PMID 35874688, 2022). "COVID-19 alters innate immune responses by viroporin-mediated NLRP3-inflammasome activation, increasing IL-1β expression." (PMID 36034552, 2022). "In the primary DILI sub-network of cluster 1, IL6, IL1B, TNF, and CCL2 were among the top ten key targets and related to the COVID-19 adverse outcome pathwaya inflammation of CRS exacerbated DILI." (PMID 35979235, 2022). "In peripheral blood immune cells and tissues of COVID-19 patients, activated NLRP3 inflammasome, caspase-1, and high levels of GSDMD-NT were found, as well as elevated expression of IL-1β and IL-18 in serum." (PMID 36532040, 2022). "Systemic levels of IL-1β, IL-6, IL-10, IL-23, IL-33 and Gal-1 were significantly higher in stage III of COVID-19 patients compared to stage I and II." (PMID 35075140, 2022). "A randomized, double-blind, placebo-controlled study revealed that nano-curcumin treatment reduced the serum levels of IL-1β, IL-6 and TNF-α in COVID-19 patients." (PMID 36263178, 2022). "In clinical applications, it has been found that severe COVID-19 patients presenting with ARDS lead to an increase in pro-inflammatory factors, most notably interleukin 1β (IL-1β), interleukin-6 (IL-6), and TNF." (PMID 35774402, 2022). "Anakinra is also used to treat COVID-19 because the macrophage NLRP3 inflammasome is activated and IL-1β production is promoted." (PMID 35464987, 2022). "The pathological feature of COVID-19 is that active viral replication activates a variety of immune cells and produces a large number of inflammatory cytokines such as TNF, IL-6, IL-1β, IL-17 and IFN-γ, resulting in cytokine storm." (PMID 35935817, 2022). "This also showed that stimulation post-BCG vaccination increased expressions of BIRC3, CCL3, CCL3L1, CCL4, CSF2, IL1B, and LTA, which in contrast, decreased in severe COVID-19." (PMID 36225326, 2022). "In male participants, EGF, GM-CSF, IL-1ra, IL-1α, IL-1β, IL-2, IL-4, IL-7, IL-15, EOTAXIN, MDC, MIP-1α, MIP-1β, IFNα2, and sCD40L were significantly lower in COVID-19 patients compared to controls." (PMID 36554094, 2022). "Local or systemic cytokine release is typical with COVID-19 and interleukin (IL)-6, IL-1β, and tumor necrosis factor-α (TNF-α) play key roles in the progression and exacerbation pathogenesis of COVID-19." (PMID 36590587, 2022). "Overall, studies suggest that type I IFN responses are dysfunctional in severe COVID-19 and correlate with TNF- and IL-1β-driven inflammation in patients with severe disease." (PMID 35244141, 2022). "A recent study using artificial intelligence techniques revealed that genes involved in activation of immune pathways (IL-6, TNF, JAK2, IL-1B, SERPINE1, TGFB1, CD8A, and VWF) serve as major hubs in the COVID-19- thrombocytopenia interactomes." (PMID 35372456, 2022).
COVID-19 (continued). "Specifically, ncfDNA was correlated with cytokines/chemokines such as IL-15, IL-8, Eotaxin-3, IL-1β, IL-10, IL-16, VEGF, IL-6, IL-7, GM-CSF and IL-1α in SOTRs with COVID-19." (PMID 35075453, 2022). "In contrast to the cases with severe COVID-19 and MIS-C, IL-6 and IL-1β levels were normal in MIS-A cases." (PMID 35601440, 2022). "Our results revealed that exosomes from severe COVID-19 patients trigger (i) NLRP3, caspase-1, and IL-1β transcription; (ii) NLRP3 inflammasome activation; and (iii) maturation and secretion of IL-1β from endothelial cells." (PMID 35587188, 2022). "A similar hyper induction of proinflammatory cytokines, such as IL6, IL1B, and IFNG, was observed in COVID-19 patients, and the level of induction in these cases was proportional to the severity of the disease." (PMID 35740365, 2022). "This cytokine storm causes an increase in T-helper (Th)-1 cytokines, including TNF-α, IL-1β, CCL2, CXCL10, IL-6, and IFN-γ, and Th-2 cytokines, including IL-10, IL-4, and IL-1 receptor antagonists in the serum of COVID-19 patients." (PMID 35053059, 2022). "Controversially, another study indicated that in severe COVID-19 cases, peripheral blood monocytes significantly increased expression of IL-6, TNF, IL-1β, and their receptors, as well as pro-inflammatory chemokines including CCL2, CCL3, and CCL4." (PMID 35632823, 2022). "An increased concentration of IL-6, TNF-α, IL-2, IL-8, IL-1β, G-CSF, IL-17, GM-CSF, IL10, MCP1, MIP1α, chemokines, galectins in serum, was detected in COVID-19 patients." (PMID 35075140, 2022). "Analysis of cytokine and chemokine expression levels revealed higher IL-1β, IL-6, TNF, and CCL2, CCL3, CCL4, and CCL7 in severe COVID-19 BALF compared to moderate disease." (PMID 35401519, 2022). "The results showed an elevated concentration of IL-1β, IL-6, TNF-α, IL-2R, IL-17, and IL-10 cytokines in the serum of COVID-19 patients." (PMID 35842705, 2022). "Pro-inflammatory genes like IL1B of IRF1 were downregulated, as well as HLA genes, in agreement with previous studies, suggesting decreased antigen presentation in severe COVID-19 patients." (PMID 36443794, 2022). "This framework releases large amounts of pro-inflammatory cytokines, as in COVID-19, including IL-6, TNF, IL-1β, IL-12, IL-17, IL-18, IP-10, IFN-γ, CCL2 and CCL5." (PMID 35843719, 2022). "In COVID-19 patients, excessive release of cytokine, including IL1-β, IL-2, IL-6, IL-7, IL-8, IP10, MCP1, MIP1A, and tumor necrosis factor-α (TNF-α), exacerbated COVID-19 manifestation." (PMID 36203683, 2022). "Severe COVID-19 manifested as ARDS with elevated pro-inflammatory cytokines, involving TNF-α, IL-6, IL1B, and CCL2." (PMID 35227280, 2022). "An increased expression of CCL3, CCL4, CSF2, IL1B, and LTA was found in the revaccinated groups (groups 5 and 6), which in fact experienced decreased expression in severe COVID-19 patients." (PMID 36225326, 2022). "During COVID-19, the NLRP3 inflammasome is overactivated, leading to the production of IL-1β/18 and promoting cytokine storm." (PMID 36034710, 2022). "Such interleukins as IL-1β, IL-6, IL-17A, TNFα, and monocyte chemoattractant peptide (MCP)-1 were identified in patients with severe COVID-19." (PMID 35213582, 2022). "A potential activator of NLRP3 is reactive oxygen species (ROS), so it is thought that their excessive production resulting from inflammation in COVID-19 leads to NLRP3 activation and cleavage of the IL-1β precursor which potentiates inflammation." (PMID 35562935, 2022). "In cluster 1, IL6, IL1B, TNF, and CCL2 of the top ten key targets were enriched in COVID-19 adverse outcomes pathway, indicating the exacerbation of COVID-19 inflammation on DILI." (PMID 35979235, 2022). "NLRP3 inflammasome activation primed and stimulated host inflammatory response, and the inflammatory cytokines (including IL-1β, IL-2, IL-6, IL-8, IL-18, and TNF-α) have been identified to be related to disease severity in COVID-19 patients." (PMID 34979342, 2022).
COVID-19 (continued). "Here, we report a preliminary study aimed at the characterization of the lung inflammatory context in COVID-19 patients, with a special focus on IFN-λ and IL-1β." (PMID 36422642, 2022). "Consistently, our data of NLRP3 showed a positive correlation with IL-1β, as suggested by previous studies where NLRP3 role in COVID-19 is highlighted." (PMID 35812405, 2022). "There is plenty of evidence that elevated levels of different cytokines like IFN-γ, IL-6, IL-1β, IL-10 and MCP-1 are higher in COVID-19 patients." (PMID 36466830, 2022). "Co-targets were 194 genes intersecting with COVID-19, RA-DEGs (GSE55235), and pyroptosis-related genes, including 7 genes: CASP1, CASP8, IL1B, CASP3, JUN, EGFR, CXCL8." (PMID 36532040, 2022). "Currently, several therapies are used for the COVID-19 treatment to reduce the overwhelmed inflammation and the SARS-CoV-2-mediated activation, such as IL-1β inhibitors, IL-6 inhibitors, JAK-inhibitors, and corticosteroids." (PMID 36148228, 2022). "Inflammation is the major pathological response of the body after SARS-CoV-2 infection, in which elevated cytokine levels, such as IL-1β, IL-6, TNF-α, NOS2 and CCL2 are often observed in COVID-19 patients." (PMID 35897044, 2022). "Only levels of IL1B, neutrophil chemotactic CXCL8, and alarmins S100A8/S100A9 were comparably elevated in KD and COVID-19 compared to their respective controls." (PMID 36159873, 2022). "In contrast, G-CSF, IL-1RA, IL-17a, IL-1b, INFγ, MCP3 and TNFα were undetectable or negligible in the serum and CSF of both the HC and the COVID-19 group." (PMID 35479062, 2022). "Based on the COVID-19 cytokine literature, we identified 6 cytokines (IL-1β, IL-2, IL-6, IL-8, IL-10, and TNF-α) commonly found in critically ill COVID-19 patients." (PMID 35033181, 2022). "A study of a longitudinal serum cytokine analysis of 207 COVID-19 patients showed that in very early inflammatory responses, IL-6, TNF-a, IL-10, and IL-1b rose in those with more severe disease." (PMID 35223745, 2022). "• IL-6 plays a main role in COVID-19 severity, while TNF-α and IL-1β trigger the NF-κB signaling pathway." (PMID 35422702, 2022). "Unexpectedly, pro-inflammatory monocyte markers such as IL1B and TNF are downregulated in COVID-19 monocytes relative to controls, both in progressive and in stable patients, although IL1B was slightly less downregulated in stable patients." (PMID 35064122, 2022). "Serum levels of EGF, G-CSF, GM-CSF, IL-1ra, IL-1α, IL-1β, IL-2, IL-4, IL-7, IL-8, EOTAXIN, fractalkine, GRO, P-10, MDC, MIP-1α, MIP-1β, IFNα2, and sCD40L were significantly lower in female COVID-19 patients compared to controls." (PMID 36554094, 2022). "Patients with severe COVID-19 exhibit substantial immune changes including lymphopenia and increased blood levels of inflammatory biomarkers such as C-Reactive Protein (CRP), IL-1β, TNF-α, IL-8, and IL-64–8." (PMID 35064122, 2022). "Increased pro-inflammatory cytokine, IL6, IL1-β, and IP10 expression in COVID-19 patients promotes neutrophil proliferation and infiltration into the lung for injury." (PMID 35784278, 2022). "Morphometry-based microscopic analysis revealed that the immunohistochemical reaction generated by antibodies against TNF-α, IL-1β, IL-15, IL-6, MCP-1, CD8, CD20, and CD45 was significantly different between the COVID-19 group and the control group." (PMID 34463916, 2022). "In fact, many of the components of the cytokine storm described in COVID-19 such as IFN-γ, IL-1β, IL-6, IL-17, and TNF-α can directly induce SkM fiber proteolysis and decrease protein synthesis." (PMID 35625805, 2022). "In this study, we evaluated the expression of the immune–inflammatory mediators IL-1β, IL-6, IFN-β, and IFN-λ in postmortem lung specimens (i.e., the natural site of SARS-CoV-2 infection) of patients who died because of severe COVID-19 and control subjects." (PMID 36422642, 2022).
COVID-19 (continued). "IL-6, IL-8, IL-10, and TNF-α were increased in severe cases of COVID-19 while IFN-α, IL-1β, IL-4, and IL-15 were enriched in mild cases." (PMID 35685940, 2022). "Noteworthily, IL6, IL1B, TNF, and CCL2 in the COVID-19 adverse outcome pathway were found to be the DILI targets, indicating exacerbation of these inflammatory factors of CRS on DILI." (PMID 35979235, 2022). "We began by examining serum levels of IL-1β, IL-6, IL-10 and TNFα at ICU admission in all serum samples from our Cytokine Cohort of 90 COVID-19 patients." (PMID 36451808, 2022). "On the contrary, we saw a difference in terms of TNF-α levels (higher in HIV/COVID-19 than in HIV group) and IL-1β (higher in the HIV group than in the group of coinfected participants)." (PMID 35891555, 2022). "In contrast, we found that plasma IL-6, IFN-α, IFN-γ, IL-1β, TNF-α, IL-10, IP-10, MIG and MCP-1 levels were significantly higher in severe COVID-19 compared to healthy controls." (PMID 35422799, 2022). "In COVID-19 patients, high levels of TNF-α, IL-1β, IL-4, IL-6, IL-10, IP-10, MCP-1, and MIP-1A have been detected, and particularly, high IL-6 concentrations are positively correlated with the severity of the disease." (PMID 35744777, 2022). "The CS of severe influenza and COVID-19 concurs in elevated PRR- and inflammasome-induced cytokines, such as TNFα, IL-1β, and IL-6, revealing a persistent innate inflammatory reaction that is detrimental to the host." (PMID 35674675, 2022). "In contrast, the COVID-19 vaccines containing N1mψ-modified mRNA, formulated in LNPs containing either MC3 (BioNTech) or SM-102 (Moderna), were able to induce IL-1β in human PBMCs." (PMID 35890284, 2022). "In this study, a considerable rise in serum LDH, troponin I, CK-MB, IL-1β, IL-4, IL-10, IL-17, and INF-γ levels was recorded in COVID-19 patients compared to healthy controls." (PMID 35891209, 2022). "Our multivariate model showed that COVID-19 was related to increased expression levels of TNF-α, IL-1β, IL-6, IL-8, IL-12B, and IL-10 (P < 0.05), and that leprosy simultaneously enhanced the levels of IL-6 (P = 0.046) and IL-12B (P = 0.020)." (PMID 33819170, 2021). "The analysis of the immune characteristics of patients with severe COVID-19 revealed significantly upregulated levels of cytokines, including IL-6, TNF-α, IL-1β, and IL-8, among others." (PMID 34360706, 2021). "The proinflammatory cytokines TNF-α, IL-1β, IL-8, IL-6, and IL12-B (P < 0.05) were increased in patients who had contracted COVID-19." (PMID 33819170, 2021). "Our data show increased cytokine and chemokine gene expression, including CXCL8, IL-1β, and CCL3 (MIP-1α) in both mild and severe COVID-19, compared to healthy controls." (PMID 34108966, 2021). "During the early stage of the pandemic, the upregulation of many cytokines, including interleukin (IL)-6, IL-1β, tumor necrosis factor α (TNF-α), and interferons, was observed in patients with COVID-19." (PMID 34001144, 2021). "It was reported significantly increased plasma levels of pro-inflammatory cytokines, including IL-1β, IL-6, IL-7, IL-8, IL-9, IL-10, interferon (IFN)-γ, and TNF-α in patients with COVID-19 than in healthy adults, but similar levels of IL-5, IL12p70, and IL-15." (PMID 34595175, 2021). "In critical COVID-19 patients, a rise in serum IL10 levels occurs subsequently to elevated levels of innate inflammatory molecules IL-1β, IL-6, IL-8, and sTNFR1 during the course of the infection." (PMID 34829906, 2021). "A variety of proinflammatory cytokines, such as IL-1β, IL-6, IL-8, and IFN-γ, were elevated in severe COVID-19 patients and active AOSD patients, suggesting a common link of the cytokine storm in the pathogenesis of both diseases." (PMID 34239943, 2021). "An upsurge of IL-1β, IL-18, and LDH (Lactate dehydrogenase) has been reported in sera of COVID-19 patients, which hints the involvement of the inflammasome network." (PMID 33467177, 2021).